MICA (MHC class I polypeptide-related sequence A)
Diseases named in the same sentence as MICA in open-access papers (continued):
Sharing a sentence is not in itself a finding about the gene and the disease.
melanoma (continued). "Mice with ubiquitous enforced expression of MICA that triggered chronic stimulation through NKG2D exhibited NK cells with reduced expression of NKG2D, and these NK cells exhibited an impaired NKG2D-dependent NK cell-mediated cytotoxicity and accelerated growth of a MICA-expressing melanoma." (PMID 34394116, 2021). "Indeed, MICA expression on melanoma cell lines FM55m1, FM86, FM78, and SK-MEL-28, colorectal cancer cell lines HT29 and SW480, as well as HeLa and HaCaT cells were sensitive to ACLY inhibition by HC." (PMID 32849657, 2020). "Interestingly, EVs obtained from certain melanoma cell cultures also contain NKG2D-ligand MICA, and these EVs can diminish the surface expression of the receptor on NKs." (PMID 33138017, 2020). "Investigations into the mechanism of this IFN-γ-mediated downregulation revealed that IFN-γ induced the expression of miR-520b, a miRNA that targets the 3′ UTR of MICA mRNA transcripts in a range of cancer cell lines including melanoma, HeLa, breast and colorectal." (PMID 33352921, 2020). "In consequence, recent in vitro data has shown that, under pressure of the BRAF inhibitor Vemurafenib (PLX4032), human melanoma cells downregulate B7-H6, MICA, ULBP2 and the DNAM-1 ligand CD155, and upregulate MHC class I expression, in order to escape NK-cell mediated tumor cell recognition." (PMID 30871206, 2019). "Interestingly, rescue with anti-MICA antibody was only achieved for the melanoma cells, consistent with our finding that MICA is released only from melanoma cells in significant quantities." (PMID 30908480, 2019). "In mouse melanoma cell lines, CEACAM1-4L isoform downregulates cell surface levels of NKG2D ligands MICA and ULBP2 while CEACAM1-3S and -3L overexpressions in CRC cell lines cause sequestration of MICA/B intracellularly, preventing it from activating NK cells." (PMID 30406153, 2018). "We thus hypothesized that high levels of active MMPs secreted by our melanoma-associated fibroblasts could induce the observed decrease of MICA/B and shedding at the surface of the T1 melanoma tumor cells." (PMID 28423623, 2017). "Of note, since NKG2D on some CD8+ T cells can trigger a co-stimulatory signal, CAF-dependent decrease of MICA/B expression at the surface of melanoma tumor cells might also affect the T cell-dependent immune response." (PMID 28423623, 2017). "Similar to the results from the analyses of the MCC tumor samples, MICB mRNA expression was low, but still higher than MICA mRNA, with relative expression ranging from approximately 0.02 to 0.48 when calibrated to the positive control melanoma cell line IF6’s mRNA expression." (PMID 26902929, 2016). "This, together with the frequent expression on melanoma cells of ligands recognized by major activating NK receptors (including MICA/B, ULBPs, PVR, Nectin-2 and B7H6), suggests that NK cells may indeed represent important effectors against this tumor." (PMID 27563819, 2016). "MICA/B expression was observed at a higher frequency than ULBP2 on melanoma metastasis." (PMID 26779186, 2015). "The expression of MICA/B on melanoma cell lines prevailed over ULBP expression." (PMID 26779186, 2015). "The respective roles of signaling pathways involving PPARγ and SAPK/JNK in melanoma development and in MICA expression are still unknown and should be analyzed in further studies." (PMID 23493799, 2013). "Interestingly, this MICA overexpression makes melanoma cells more sensitive to in vitro lysis by NK cells." (PMID 23493799, 2013). "Interestingly, this weak MICA overexpression was able to enhance melanoma cell sensitivity to NK cell lysis in vitro." (PMID 23493799, 2013). "Interestingly, the immune therapy against melanoma patients induced the production of auto-antibodies against MICA." (PMID 23024757, 2012). "In addition, VSV10 infection significantly down modulated the constitutive surface expression of MICA/B on the two melanoma cell lines, FM-86 and FM-78." (PMID 21857986, 2011).
melanoma (continued). "We were not able to detect significant concentrations of plasma TGF-β or serum MICA/B in our 14 melanoma patients that could account for the low expression of NKG2D receptors (not shown)." (PMID 19319200, 2009). "Thus, an increase in the number of NKG2D receptors on sNK cells and increased MICA/B on melanoma tumors during sNK cell interaction could contribute to increased efficacy of sNK cells against melanoma tumors compared to primary NK cells." (PMID 40805135, 2025). "Moreover, the imbalance between activating and inhibitory signals decreases NK cell cytotoxicity against malignant cells, supported by a less robust activity of tissue-infiltrating NK cells in solid tumors and low levels of MICA and ULBP expression in some B2M-deficient melanoma cell lines." (PMID 36046045, 2022). "In addition, MICA+ EVs from this melanoma cell line contained more CD81 than CD9." (PMID 36726591, 2022). "Indeed, this correlation between expression of MICA/B and survival has been reported in a wide range of human carcinomas, including colorectal-, hepatocellular-, pancreatic-, gastric-, and lung carcinoma as well as melanoma." (PMID 29221214, 2017). "Moreover, a number of positive and negative associations with specific MICA alleles were revealed by comparing melanoma patients with healthy individuals." (PMID 25838620, 2015). "However, to date, no studies have been performed on MICA polymorphism in the extracellular domains in melanoma." (PMID 25838620, 2015). "However, the influence of MICA polymorphism in extracellular domains (exons 2, 3, and 4) has not been investigated on melanoma disease." (PMID 25838620, 2015). "In melanoma, the IRE1α–XBP1 axis inhibits the E2F1 binding site on the MICA promoter, consequently suppressing MICA expression, while the expression of ULBP proteins remains unaffected." (PMID 40547943, 2025). "Consistent with results from GDC TGCA SKCM data base, we observe a correlation between high MICA/MICB serum levels and poor OS as well as PFS in a cohort of patients with advanced melanoma." (PMID 39837817, 2025). "Melanoma tumors can escape NK cells’ recognition by cleaving and shedding the soluble forms of NKG2L, such as MICA/B and ULBPs." (PMID 40805135, 2025). "The effects of IL-10 on NKG2DL expression are complex: it downregulates MICA and upregulates MICB expression on melanoma cells and increases NKG2DL levels on macrophages." (PMID 37626965, 2023). "There is a study suggesting that CEACAM1, particularly the CEACAM1-3S isoform, was able to induce enhanced expression of the NKG2D ligands MICA and ULBP2 on the surface of melanoma cells, which in turn contributed to NK cell-mediated cytolysis of tumor cells." (PMID 36712923, 2023). "Other receptors such as MHC class I chain related-proteins A (MICA) and B (MICB) or MICA/B, NKp30, NKp44, and NKp46 have been also expressed in melanoma cell lines." (PMID 36434591, 2022). "This work also shows that BRAFi and MEKi, as solo or combined treatments in vitro, decreased soluble MICA, MICB and ULBP2 in supernatants from BRAF-mutant melanoma cells." (PMID 36726591, 2022). "CEACAM1-3S is associated with enhanced immunogenicity and contributes to improved OS of patients with advanced melanoma; in contrast, CEACAM1-4L promotes tumor progression by downregulating the cell surface expression of the NKG2D ligands MICA and ULBP." (PMID 36438905, 2022). "In melanoma, statin therapy induces MHC class I Chain-related protein A (MICA) overexpression and increases the sensitivity of NK cells to tumor cell killing." (PMID 34858839, 2021). "As a consequence of the BRAF inhibitor treatment, activating ligands MICA, ULBP3 and PVR are decreased on melanoma cells, thus contributing to diminished NK cell activation and further support of immune escape." (PMID 34572949, 2021).
melanoma (continued). "The release of active MMPs by MAFs decreases the expression of the two NKG2D ligands, MICA/B, on melanoma cell surfaces and consequently reduces the NKG2D-dependent cytotoxic activity of NK cells against melanoma cells." (PMID 34067929, 2021). "Given the critical role of MICA and MICB in the innate immune response to melanoma, we initially used an ELISA assay to examine the amount of MICA in the medium of irradiated cells compared to the non-irradiated control." (PMID 33789714, 2021). "In fact, blocking MICA and MICB shedding from the tumor surface reduced melanoma metastasis and improved the antitumor immunity in an NKG2D- and CD16-dependent manner." (PMID 33802954, 2021). "To assess MICAgen mice for both functional NKG2D-mediated immunorecognition of MICA+-tumors and for immunotolerance toward the xenoantigen MICA, we used B16F10 melanoma cells ectopically expressing human MICA*001." (PMID 32582150, 2020). "In melanoma, IFN-γ triggers signal transducer and activator of transcription-1 signaling, which lowers the expression of MICA mRNA and blocks MICA expression in tumor cells." (PMID 30813924, 2019). "This secretion reduces the expression of the two NKG2D ligands, MICA/B, at the surface of tumor cells and consequently decreases the NKG2D-dependent cytotoxic activity of NK cells against melanoma tumor cells." (PMID 28423623, 2017). "We therefore performed qRT-PCR with MICA and MICB mRNA specific primers using the melanoma cells FM79, FM82 and IF6 as positive controls." (PMID 26902929, 2016). "Serum CEACAM1, MICA and MICB were previously reported as poor prognostic markers in melanoma, but the relevance of pericardial involvement has never been evaluated." (PMID 26909604, 2016). "Soluble NKG2D ligands MICA and ULBP2 are released by melanoma cells and can down-regulate the expression of NKG2D on effector cells." (PMID 26779186, 2015). "These MMPs promote the detachment of MHC class I polypeptide-related sequence A and B (MICA/B), ligands of NKG2D (Natural killer group 2 member D), from the surface of melanoma cells, weakening the NKG2D-mediated cytotoxic response of NK cells against tumor cells." (PMID 40399946, 2025). "Additionally, we examined the MICA/MICB-NKG2D axis, a crucial mechanism for NK cell-mediated tumor recognition and killing, and found that CCNB1-high melanoma cells suppress its activation." (PMID 40430484, 2025). "Nonetheless, our study provides the first evidence of a direct relationship between androgens and MICA/B shedding by ADAM10 in melanoma, which is classically considered a ‘non-hormone dependent cancer’." (PMID 39837817, 2025). "Thus, MICA shedding and NKG2D downregulation are involved in the androgen-induced immune escape of melanoma cells." (PMID 39837817, 2025). "Inhibition of BRAF with vemurafenib led to reduced MICA and ULBP2 expression by melanoma cells." (PMID 37626965, 2023). "In addition, proteolytic shedding of the NKAR ligands MICA, ULBP2, and B7-H6 was often observed in melanoma samples." (PMID 38067178, 2023). "On the contrary, a recent study on exosomes from melanoma patients revealed that although melanoma exosomes could induce NKG2D downregulation on NK cells, but this effect is unrelated to exosomal MICA/B." (PMID 35031075, 2022). "MICA (but not MICB) was also present in melanoma EVs isolated from plasma of melanoma patients and these EVs downregulated NKG2D in primary human NK cells, suggesting functional impairment." (PMID 36081494, 2022). "Consistent with this, high serum concentrations of shed MICA are associated with disease progression in many human cancers, including melanoma, where vemurafenib and histone deacetylase inhibitors (such as sodium butyrate) differentially modulate expression of NKG2D ligands such as MICA." (PMID 33789714, 2021). "Shedding of ligands MICA, ULBP2, and B7-H6 has been observed in melanoma patients." (PMID 34572949, 2021).
melanoma (continued). "We demonstrated that premalignant quiescent melanocytic nevi, benign lesions of the skin and normal skin do not express MICA, in opposition to a primary recently diagnosed melanoma." (PMID 34394116, 2021). "Furthermore, IFN-γ decreased transcription of MICA, ULBP1 and ULBP2 in patient-derived melanoma and glioma cell lines in a dose- and time-dependent fashion." (PMID 33352921, 2020). "Melanoma patients benefit from the expression of CEACAM1-3S as a consequence of enhanced expression of the NKG2D ligands MICA, ULBP2 and DNAM-1 ligand CD155 on the surface of melanoma cells, thus presenting these cells as targets for NK cell mediated cytolysis." (PMID 30871206, 2019). "Re-stimulation of TILs from a MICA overexpressing human melanoma through their TCR showed that they have a reduced capacity to produce IFNγ compared to TILs derived from melanoma that did not express NKG2D ligands." (PMID 29568297, 2018). "MICA expression on melanoma-derived exosomes could be detected by LFIA using anti-CD9 for capture and anti-MICA for detection." (PMID 29720199, 2018). "Nevertheless, when melanoma-derived exosomes were co-cultured with NK cells, the NKG2D receptor was downmodulated from NK cell surface, demonstrating that endogenously expressed MICA is exposed on the exosome surface and that it is biologically functional." (PMID 29720199, 2018). "IFN-γ was shown to decrease MICA and, in some cases, ULBP2 expression on human melanoma cell lines; Type 1 interferons can reduce H60 expression in the methylcholanthrene (MCA)-induced mouse model of fibrosarcoma or increase MICA/B surface expression on human pancreatic cancer cell lines." (PMID 30150983, 2018). "Of these five members, MICA and MICB are the only functional genes, which are frequently expressed by carcinomas of the breast, lung, colon, ovary, kidney, prostate, as well as in melanomas, gliomas, and leukemia." (PMID 29221214, 2017). "A combination of cDNA arrays, immunohistochemistry, serology and immunological methods recently identified a combined overexpression signature of MICA, ULBPs and PVR in early-passage melanoma cells as compared to autologous normal melanocytes from the surrounding, intact skin of melanoma patients." (PMID 26427039, 2015). "Thus, MICA and NCR ligand expression is lower in metastatic melanoma compared to primary melanoma lesions." (PMID 26779186, 2015). "The innate immune response of nude mice could be tested against human melanoma cells because these mice have NK cells bearing NKG2D receptors, which are able to recognize human antigens, like MICA." (PMID 23493799, 2013). "The impact of statin treatment on in vivo development of melanoma tumors and metastases was investigated in nude mice, because murine NK cells, which express NKG2D receptors, are able to recognize and kill human tumor cells expressing MICA." (PMID 23493799, 2013). "In two human melanoma cell lines, we showed that statin treatments were not toxic at the doses used and that they weakly and reproducibly upregulated MICA expression, which is a critical target for anti-tumor NK cells." (PMID 23493799, 2013). "MICA is frequently expressed in many, but not all, lung, breast, kidney, ovarian,prostate, gastric, and colon carcinomas and melanomas." (PMID 22475346, 2012). "It has also been shown that some MICA expressing melanoma cell lines do not necessarily express significant levels of MICA at the cell surface." (PMID 19223974, 2009). "In the presence of the BRAFi vemurafenib, BRAFV600E-mutant melanoma cells displayed strong downregulation of the NKAR ligands MICA, CD155, and B7-H6, which may result in melanoma cell resistance towards NK cell cytotoxicity as a direct byproduct of acquired BRAFi resistance." (PMID 38067178, 2023).
melanoma (continued). "In our study, ovarian and melanoma tumour cells with a platelet cloak could be induced to release soluble NKG2DL into the tumour cell microenvironment and that NKG2D was actively suppressed using recombinant MICA and MICB proteins." (PMID 30908480, 2019). "Also the NK activating ligand MICB was induced/up-regulated by guadecitabine and DAC treatment in 57.1% (8/14) and by AZA in 14.2% (2/14), while MICA was up-regulated (FC ≥2) by guadecitabine and DAC treatment in 14.2% (2/14) and by AZA in 7.1% (1/14) of melanoma cell lines." (PMID 30581389, 2018). "In contrast, no changes in MICA/B were found on other tumor cell lines (renal cell carcinoma (RCC), melanoma, and bladder cancer) treated with doxorubicin." (PMID 33572396, 2021). "Additionally, VSVΔM51 infection inhibited endogenous MICA/B and ULBP-2 surface expression on Jurkat T-cells (data not shown) and constitutive MICA/B surface expression on the two melanoma cell lines, FM-86 and FM-78." (PMID 21857986, 2011).